MYC (MYC proto-oncogene, bHLH transcription factor)
Diseases named in the same sentence as MYC in open-access papers (continued):
Sharing a sentence is not in itself a finding about the gene and the disease.
tumor (continued). "CYC065 induced significant tumor growth inhibition and increased overall survival in mice carrying MYCN-amplified Kelly NB tumor xenografts, but had weaker effects against non–MYCN-expressing SK-N-AS NB tumor xenografts, consistent with the modest effect on c-MYC levels." (PMID 33016930, 2020). "In view of the tumor‐suppressive potential of BASP1 in human cancer, small compounds or peptides based on the BASP1 ED structure could be developed to expand the spectrum of therapeutic approaches for the treatment of cancers with high MYC expression." (PMID 31944520, 2020). "Hence, MYC and TWIST1 overexpression in cancer may be eliciting tumor invasion by activating embryonic programs that otherwise physiologically enable mesodermal migration." (PMID 31933479, 2020). "The increased serum IL-6 activated STAT3/c-MYC signaling in peripheral monocytes, enhanced the transcription of miR-25–3 p, suppressed PTPRO expression, promoted PD-L1 through both JAK2/STAT3/c-MYC and JAK2/STAT1 signaling, and promoted tumor growth by enhancing T-cell exhaustion." (PMID 32581055, 2020). "Therefore, Twist1 drives metastasis of MYC-induced HCC without affecting primary tumor burden, MYC expression, tumor cell proliferation, apoptosis, invasiveness or EMT markers." (PMID 31933479, 2020). "Although this may support the idea of tumor cells being addicted to MYC/MYCN signaling, such strategy should be taken with caution, as the authors showed increased resistance to apoptosis and ionizing radiation upon MYC suppression." (PMID 33585252, 2020). "The correlation between VAV2 transcript levels and the c-MYC- and YAP/TAZ-regulated gene signatures is lost in most cases when the hnSCC samples are not stratified according to HPV status, further linking this Vav2Onc-driven pathobiological program to HPV– tumor cases." (PMID 32963234, 2020). "It is possible that following DENA-induced initiation of hepatocarcinogenesis, once the size of the tumor increases and the availability of nutrients becomes limiting, p62 increase can represent an advantage for tumor cells, as it is able to drive autophagy and activate mTORC, NRF2 and MYC." (PMID 32824383, 2020). "While its role in tumor progression is still underexplored, a recent study revealed that ARPP19 mRNA expression is an independent predictor for relapse in AML, and it might promote cell survival by regulating CIP2A and MYC expression." (PMID 32110991, 2020). "Interestingly, c-MYC expression induces angiogenesis in combination with HIF-1α and VEGF and recruits tryptase positive mast cells into the tumor niche, therefore, MYC inhibition may have a potential anti-cancer effect." (PMID 33469537, 2020). "Interestingly, a risk-SNV rs6983267 also contributes to increased expression of CCAT1; an adjacent lincRNA of CCAT2, through affecting the long-range chromosomal interaction of MYC enhancer or CCAT1 promoter, then results in a cell-cycle regulation and tumor development." (PMID 32523949, 2020). "Furthermore, targeting the MYC paralog-PARP1-DDR axis via concurrent inhibition of BET and PARP1 resulted in synergistic anti-tumor activity in vitro and in vivo against MYC paralog-driven SCLC cells, but not against MYC paralog-independent SCLC cells." (PMID 33134168, 2020). "In view of the tumor‐suppressive role of BASP1 which was recently also reported for human cancer, small compounds or peptides based on the BASP1 effector domain could be used in drug development strategies aimed at tumors with high MYC expression." (PMID 31944520, 2020). "Observations made with BET inhibitors JQ1 or OTX015 targeting both c-MYC and MYCN warrant additional studies using MYCN specific inhibition such as HUWE1 inhibitors or specific knockdown to differentiate the relative importance of c-MYC and MYCN in ATL tumor cells survival and proliferation." (PMID 32907612, 2020).
tumor (continued). "In this study, we uncover an important function of SMS in cooperation with MYC to repress Bim expression through distinct regulatory pathways, and highlight the downregulation of Bim as a key survival signal downstream of oncogenic MYC and SMS signaling to facilitate CRC tumor growth." (PMID 32591507, 2020). "It is likely that METTL3 promote the expression of SOX2 and MYC through m6A-based posttranscriptional regulation as well as AFF4-mediated regulation at the transcriptional level, which reinforces the signal activating the tumor-initiating and self-renewal capabilities of BCa cells." (PMID 32676121, 2020). "In the sample from relapsed tumor, there exist some large signals for EGFR, CDK6, and MYC along with the widely distributed smaller signals consistent with eccDNA; therefore, we cannot rule out the possibility that HSR may co-exist with double minutes at this time." (PMID 30267146, 2019). "Furthermore, with Co-IP experiment, we found that CDK5 was correlated with the anergy of BIN1/c-MYC interaction, suggesting that CDK5 could neutralize the tumor-suppressing effect of BIN1 via inducing phosphorylation of c-MYC at Ser-62 site." (PMID 31496920, 2019). "Therefore, we anticipate that ATC, in which MYC expression was activated, would also elevate LAT1 expression, and then the inhibition LAT1 signaling may lead to tumor regression in ATC." (PMID 31601917, 2019). "While N1ICD+MYC tumours resembled the metabolic phenotype observed in human SCCs, comparing the expression of metabolic genes in N1ICD+MYC lung tumours and lung tumours induced by MYC alone showed that the expression of some signature enzymes was similar between the two types of tumours." (PMID 31114017, 2019). "Thus, we reasoned that reduced c-MYC expression is not a driver of the tumour suppressive activity of CR-31 in PDA cells." (PMID 31723131, 2019). "Thus, it may be that oncogenes such as c-MYC, activate Pol-III expression during tumor initiation, mimicking developmental and homeostatic scenarios where Pol-III activity is required." (PMID 30858608, 2019). "When the MYC+N1ICD mice were injected with [U-13C]-glutamine, blood glutamine enrichment was not significantly different but Krebs cycle intermediates in MYC+N1ICD tumours showed increased percentage of 13C enrichment, particularly for 13C5-citrate, reminiscent of the SCC tissue slices." (PMID 31114017, 2019). "Finally, the percentages of S-phase cells in LMP2A/λ-MYC/p27Super and λ-MYC/p27Super mice were not significantly different (18% and 20%, respectively), compatible with the similar tumor onset observed in these two genotypes." (PMID 30992353, 2019). "There was no indication of tumor growth in any tissue after transplantation of c-MYC-MSC in mice." (PMID 30836996, 2019). "Moreover, according to the latest promoter competition mechanism, the PVT1 promoter, as a “non-standard” tumor suppressor, is a novel candidate for designing a new therapeutic strategy for tumors in which MYC serves as a carcinoma driver." (PMID 31309249, 2019). "However, studies by our group and others suggest that MYC alone is not sufficient to promote tumor growth." (PMID 30659187, 2019). "In addition, most cancer cell line models do not accurately reflect human tumours in vivo, are derived from already fully transformed tumour tissue, and are not necessarily driven by or dependent on deregulated MYC." (PMID 31350286, 2019). "Consequently, BET inhibitors inhibited the activation of AKT, mTOR, and MYC due to PI3K inhibition, and combined PI3K-BET inhibition sustained PI3K pathway inhibition and enhanced tumour cell killing in a variety of tumour models, including prostate cancer, melanoma and TNBC." (PMID 35582276, 2019).
tumor (continued). "Three of the up-regulated cancer stem cell-related genes (KLF4, MYC, and SNAI1) are transcription factors involved in rearrangement of the extracellular matrix and in epithelial to mesenchymal transition (EMT), processes that are important in tumor angiogenesis, invasion, and metastasis." (PMID 29765518, 2018). "This indicates that the repertoire of tumor transformed T cells in this experimental setting is polyclonal in turn suggesting that genetic aberrations in addition to overexpression of MYC, AKT and BCLXL would not be required for tumor transformation of mature T cells." (PMID 29765548, 2018). "The tumor suppressor FBW7 functions as the substrate recognition component of an SKP1, CUL1, and F-box protein–type (SCF-type) E3-ubiquitin ligase complex targeting several oncoproteins, including c-MYC, NICD1 (Notch1 intracellular domain), and c-JUN, for degradation." (PMID 29346117, 2018). "Activation of the canonical WNT pathway has been described to affect proliferation and migration of various non-rhabdomyomatous tumor cells through induction of the targets such as the pro-proliferative protein MYC and the pro-proliferative and anti-apoptotic IAP-protein BIRC5 (survivin)." (PMID 30568936, 2018). "As MYC regulates glucose and glutamine metabolism and also mitobiogenesis in cancer cells, this might together with MYC-dependent PGC1β expression explain why PGC1α negative tumor cells nevertheless have functioning mitochondria and metabolism." (PMID 29361779, 2018). "In order to determine BFL1 expression levels in the different tumour cell subsets, we FACS‐sorted B220+CD19+ tumour cells and B220−CD19− nontumour cells from the spleen and B220+CD19+ and B220+CD19−CD4+ tumour cells from the thymus of diseased Eμ‐MYC/Vav‐BFL1 DT mice." (PMID 29498802, 2018). "Further studies showed that the cellular MYC gene (and its paralogs MYCN and MYCL), while having critical functions in normal animal growth and development, are subject to frequent alterations in a significant fraction ( > 30%) of human cancers comprising a wide range of tumor subtypes." (PMID 30054853, 2018). "In addition, deregulated, overexpressed MYC in several tumor types binds to low-affinity non-canonical E-boxes and associates with high-density enhancers (super-enhancers) to promote expression of distinct gene subsets." (PMID 30054853, 2018). "These cells are proliferative and display a peculiar transcriptional profile characterized by elevated MYC activity; reduction of MYC activity in these cells inhibits long-term propagation of these tumor progenitor cells but does not affect their short-term growth." (PMID 30060526, 2018). "Thanks to next generation sequencing (NGS) and circulating tumor DNA (ctDNA) studies, the authors also showed the mechanisms of resistance to anti-EGFR drugs, such as the presence of EGF-R negative tumor clones, KRAS mutation/amplifications, PTEN deletion, and NRAS/HER2/MYC amplifications." (PMID 30205505, 2018). "APA-miRNA–siRNA polyplexes systemically administered to orthotopically inoculated PDAC-bearing mice showed no toxicity and accumulated at the tumor, resulting in an enhanced antitumor effect due to inhibition of MYC oncogene, a common target of both miR-34a and PLK1." (PMID 29295989, 2018). "Aggressive tumor behavior and poor outcome is correlated with high expression of synthetic genes (ODC1, SRM, SMS, AMD1, AZIN1) and low expression of catabolic genes (OAZ1, OAZ2, SAT1, PAOX), and these were identified as direct MYC effects by promoter activity and MYCN binding studies." (PMID 29799508, 2018). "As expected, MYC expression levels were very low in non-malignant tissues compared to tumor cells." (PMID 29100357, 2017).
tumor (continued). "However, c-MYC upregulation does not fully explain the proliferation and tumor growth advantage conferred by RPL5 knockdown since it also occurs in MCF7 tumors despite c-MYC downregulation." (PMID 28147343, 2017). "Also, MYC does not seem to be overexpressed in ER− tumours in one of the clinical datasets, yet its predicted targets involved in growth and proliferation are upregulated." (PMID 28619028, 2017). "BCOR has not previously been demonstrated to control tumour cell proliferation or survival, so how BCOR loss co-operates with MYC to drive oncogenesis remains unclear." (PMID 28262675, 2017). "Interestingly, SMARCA4 (also known as BRG1) is a transcriptional regulator that can control the activity of Sonic hedgehog and GliA and their downstream targets, providing a driving force for tumor proliferation by activating mitogenic genes such as GLI1, CCND1 and MYC." (PMID 29137349, 2017). "In addition, immunohistochemical expression of FAM83H was higher in MYC-expressing tumor cells compared with adjacent non-neoplastic hepatocytes in the tissue samples obtained from the livers of Tet-O-MYC mice." (PMID 28607447, 2017). "Although MYC overexpression alone does not induce aggressive tumours, in the context of dysregulated growth signaling, the ability of MYC to amplify all active transcription could lead to tumourigenesis." (PMID 28398229, 2017). "MYC, miR-17-5p, and miR-20a are up-regulated by CCAT2 through transcription factor 7 like 2 (TCF7L2)-mediated transcriptional regulation and the interaction between CCAT2 and TCF7L2 results in an enhancement in WNT signaling activity, which promotes tumor growth and metastasis in CRC." (PMID 28108736, 2017). "In contrast, DNMT3A expression was not consistent in both MYC-driven tumor types." (PMID 29100357, 2017). "We observed no adverse effects on the quiescent host cells up to 100 μM, consistent with the fact that I-BET151 in known to be active in tumor cells and cancer cell lines in which c-MYC is overexpressed but not in a variety of other nonimmortalized cell types (18, –, 22)." (PMID 28168222, 2017). "Furthermore, in an immunohistochemistry assay, we observed that the expression levels of RTL1, c-MYC, CYCLIN D1 and β-CATENIN in tumour tissues were increased after overexpression of RTL1 and decreased with RTL1 knockdown, in agreement with previous findings in A375 cells." (PMID 29285312, 2017). "Thus, in this experimental model, HBx alone has no direct pathological effects; however, it accelerates c-MYC-induced tumor development." (PMID 28422055, 2017). "In general, cancer-related gene sets, such as MYC and E2F targets and G2M, showed a “normal-like” tendency in NAT; normal cellular differentiation pathways, such as adipogenesis and myogenesis, showed a “gradient” tendency; and inflammatory-related pathways showed a “tumor-like” tendency." (PMID 29057876, 2017). "The combined effects of BRD4 and CDK9 inhibition on blocking tumor cell proliferation might be independent of the MYC- expression, as H1792 is a MYC-amplified cell line and HeLa cells do not harbour any MYC alteration." (PMID 29156698, 2017). "While MYC is a bona fide oncogene transcribed from the most frequently amplified locus across human cancer types, p27 does not exhibit the typical tumor suppressor properties, mostly obvious from its chromosomal locus not displaying focal and frequent deletions in cancers." (PMID 28665315, 2017).
tumor (continued). "We could, then, base our tumor selection for sensitivity on the balance between p-AKT, p-ERK, MYC or mTor, which concomitantly or independently are modulating the sensitivity to rapamycin and irinotecan, and in the absence of an isolated HIF-2α over-expression." (PMID 29069732, 2017). "A quantification of Cas3 and c-MYC signals revealed that cell death of stromal cells was highly correlated to c-MYC protein levels in the tumour cells, regardless of tumour stage and type, suggesting that MMCC may work between different cell histotypes." (PMID 28974715, 2017). "Inducing expression of oncogenes such as c-MYC or RAS in non-tumorigenic cell lines can confer colony forming ability which correlates with tumor formation in mouse xenografts demonstrating the capacity of this assay to assess conversion to a malignant phenotype." (PMID 28415575, 2017). "Aberrant activation of NF-κB pathway is observed in a variety of tumor types, which regulates a range of tumorgenic processes, including proliferation, invasion, metastasis and angiogenesis, by transcriptionally activating numerous target genes, such as CCND1, MYC, MMP9 and VEGF in cancer cells." (PMID 29044221, 2017). "Several oncogenes including MYC, hypoxia inducible factor 1 (HIF1), phosphoinositide-3-kinase (PI3K), protein kinase B (PBK or Akt) and the mechanistic target of rapamycin (mTOR), have been known to be involved in the regulation of tumor metabolic reprogramming." (PMID 28040803, 2016). "Furthermore, over-expression of SOX2, OCT4 or NANOG alone is sufficient to enhance tumorigenesis in a mouse model; up-regulation of c-MYC has been reported to increase the CSC fraction by 150-fold, enabling tumor formation and serial propagation with as few as 500 cells." (PMID 26506421, 2016). "Comparison of combined ADA3/c-MYC expression with clinico-pathological parameters showed a significant correlation of the patterns of their co-expression with tumor grade, pleomorphism, NPI status and tumor types, as well as expression of Ki67 and p27 proteins." (PMID 27852327, 2016). "It has been described that in pancreatic tumors MYC acts as a switch between the OXPHOS-dependent metabolism of cancer stem cells towards the highly glycolytic differentiated progeny, creating a gradient of heterogeneous oxidative/glycolytic population inside the tumor." (PMID 27455839, 2016). "Furthermore, CD133 depletion suppresses tumor cell proliferation, colony formation, and the expression of core stemness transcription factors including NANOG, octamer-binding transcription factor 4 (OCT4), SOX2, and c-MYC." (PMID 26539911, 2015). "Moreover, c-MYC has been described to activate the transcription of TERT, which may contribute to sustaining the proliferation of tumor cells along the cell cycle." (PMID 25889298, 2015). "Interestingly, c-MYC expression was not significantly different between normal and grade II tumor tissue samples, although there was a significant (P<0.001) increase in grade I vs normal controls)." (PMID 25901368, 2015). "Importantly, genes co-expressed with SLC16A7/MCT2 in human tumours also clustered in oncogenic-related pathways (e.g. PI3K, EGFR, KRAS) and effectors of these signalling pathways were found to bind at the SLC16A7/MCT2 gene locus (e.g. MYC, EGR1, PRDM1)." (PMID 26035357, 2015). "In these types of cancers, miR-494 functions its tumor suppressive effects, and inhibites cell proliferation, cell migration, and cell invasion and promoting apoptosis by regulating different oncogenes in different cancer cells, such as VEGF, CXCR4, CLPTM1L, HOXA10, and c-MYC." (PMID 26317788, 2015). "In addition to destabilizing c-MYC as reported herein, SIRT3 could function as a tumor suppressor possibly via its ability to deacetylate the proto-oncogene Skp2." (PMID 26317998, 2015). "Therefore, repression of MYC and BCL2L1 might contribute to the tumor suppressor effects of FOXO1 in PMBL." (PMID 24977668, 2014).